BDNF (brain derived neurotrophic factor)
Diseases named in the same sentence as BDNF in open-access papers (continued):
Sharing a sentence is not in itself a finding about the gene and the disease.
Cognitive impairment (continued). "We created a genetic risk score to represent the accumulation of risk genotypes of polymorphisms in BDNF, COMT, and APOE to test whether the risk score predicted the presence of late-life cognitive impairment above and beyond that of each individual gene polymorphism." (PMID 26366299, 2015). "Because BDNF plays a critical role in the regulation of high-frequency synaptic transmission and long-term potentiation in the hippocampus, the up-regulation of BDNF may rescue cognitive impairments and learning deficits in AD." (PMID 25849905, 2015). "The cognitive deficits of this illness, considered a core manifestation and an important predictor for functional outcome, can be understood in the context of the molecular and cellular mechanisms of learning and memory, in which BDNF plays a key role through regulation of synaptic plasticity." (PMID 23785335, 2013). "Therefore, the reversal of cognitive deficits as well as some other aspects of AD pathology by J147 may result from an up-regulation of BDNF and NGF pathways." (PMID 23673233, 2013). "This article reviews different elements that provide evidence that BDNF may play a role in pathogenesis of schizophrenia, but also reviews the evidence suggesting that it may play a role in the pathophysiology of cognitive deficits, which can be considered core symptoms of this disease." (PMID 23785335, 2013). "Previous studies have found that serum and plasma BDNF levels are lower in individuals with type 2 diabetes compared to non-diabetic individuals, posing the question of whether the higher rate of cognitive impairments in diabetes may be in part mediated by low BDNF levels." (PMID 22880108, 2012). "In these studies, BDNF levels remained elevated following treatment with CMF and DOX + CYP, respectively, while cognitive impairments persisted." (PMID 41155372, 2025). "Since BDNF-TrkB signaling is essential for neurogenesis and synaptic maintenance, these findings suggest that chronic exposure to DM and IMI may impair brain plasticity and neurodevelopment, increasing susceptibility to cognitive deficits and neurodegeneration." (PMID 40283093, 2025). "A previous study have highlighted the importance of BDNF/TrkB/CREB signaling pathway in ameliorating neuronal damage and cognitive impairment." (PMID 40534913, 2025). "Another rodent study revealed increases in BDNF and PSD-95 in the AMY and HPC reversing cognitive impairment and reducing fear memory well past ketamine’s elimination from the host body." (PMID 40097854, 2025). "It alleviated PD-related pathological impairments and cognitive deficits and promoted the secretion of FNDC5 and BDNF, producing neuroprotective effects." (PMID 41195080, 2025). "Thus, the regulation of insulin signaling and CREB/BDNF pathways in the hippocampus via SCFAs, particularly butyrate, was proposed as the mechanism by which the combination of hesperetin and metformin improved cognitive impairment in DM rats through the gut–brain–microbiota axis." (PMID 40076550, 2025). "Noteworthy, luteolin attenuates PTZ-induced cognitive deficits in rats by reducing oxidative stress and activating the PKA/CREB/BDNF signaling axis—a pathway critically involved in learning, memory, and neuronal survival." (PMID 40949124, 2025). "Therefore, BDNF signaling activators may ameliorate AD neuropathology and cognitive impairment." (PMID 40380033, 2025). "BDNF plays a vital role in neurogenesis, synaptic plasticity, cognition, and neurotransmission, with the BDNF/TrkB/CREB signaling pathway being critical for ameliorating neuronal injury and cognitive impairment." (PMID 40534913, 2025). "Our study showed a significant reduction of PKA, BDNF and CREB levels following administration of SCOP, which was in line with a previous report that SCOP promoted cognitive deficits in rodents by impairing the CREB–BNDF neurotrophic pathway." (PMID 40243772, 2025).
Cognitive impairment (continued). "Our findings indicated a significant cognitive impairment in adult PWE and reduced serum BDNF in cognitively impaired persons." (PMID 40291844, 2025). "Further, we investigated the relationship between cognitive impairment and the possible roles of serum BDNF, BACE1, VEGF, and GFAP as potential biomarkers for cognitive impairment in people with epilepsy." (PMID 40291844, 2025). "Dansheninone IIA (TSA) ameliorates Pb-induced cognitive impairment by elevating SOD and GSH levels, decreasing malondialdehyde (MDA) concentration, and synergistically enhancing brain-derived neurotrophic factor (BDNF) expression." (PMID 40951398, 2025). "These enhancements were achieved by increasing brain‐derived neurotrophic factor (BDNF) levels and reducing neuroinflammatory responses in the hippocampus of mice with cognitive impairment." (PMID 40827097, 2025). "Recently, there is increasing evidence demonstrating the relationship between BDNF/CREB/ERK and cognitive impairment." (PMID 40358798, 2025). "NaBP, by elevating the levels of neurotrophic proteins and brain-derived neurotrophic factor (BDNF) in astrocytes, exerts neuroprotection and improves cognitive impairments." (PMID 37548934, 2024). "The results demonstrated a strong direct correlation between cognitive impairment as measured by the MMSE test and the levels of TSH, fT4, anti-TG and anti-TPO antibodies, 25-OH vitamin D, and brain-derived neurotrophic factor (BDNF)." (PMID 39768799, 2024). "HNSCs improved the motor and late cognitive impairment of HD model mice by reducing the abnormal accumulation of mutant HTT protein and the expression of brain-derived neurotrophic factor (BDNF)." (PMID 38515621, 2024). "The present study showed that CSD decreased the mRNA and protein levels of BDNF, SYN, and PSD‐95 in mice, which contributed to cognitive deficits induced by CSD." (PMID 38688894, 2024). "Prior research has revealed that mumefural treatment ameliorated cognitive impairment by regulating p-ERK/ERK, p-CREB/CREB, and BDNF levels." (PMID 39203778, 2024). "Collectively, the LS group inhibited postpartum cognitive impairment by regulating the brain fatty acid composition, neuroinflammation, gut microbiota, and the SCFA/ERK(1/2)/CREB/BDNF signaling pathway compared to lard." (PMID 39203778, 2024). "We also found that the decreased expression levels of BDNF, SYN, and PSD‐95 were correlated with CSD‐induced cognitive impairment." (PMID 38688894, 2024). "Lower levels of BDNF concentration were found in those with PTSD and cognitive impairment compared to those with normal cognition in the PTSD group (p < 0.001)." (PMID 38237700, 2024). "Relative to chronic stress-induced cognitive impairment, resveratrol led to an overall cognitive enhancement in this context through its action on SIRT1 and the BDNF/CREB pathway." (PMID 39458427, 2024). "Impaired ERK/CREB/BDNF signalling pathway and an inhibition of CaMK-II/PKC/PKA-ERK-CREB signalling lead to cognitive deficit and disruption of long-term potentiation in the hippocampus." (PMID 38255283, 2024). "These include a reduction of dopamine levels in the striatum, motor deficits, neuroinflammation, reduced levels of brain-derived neurotrophic factor (BDNF), and cognitive impairment in the more advanced stages of degeneration." (PMID 38550606, 2024). "It helps to reduce cognitive impairment, neuroinflammation, and oxidative stress by activating TLR4/NFκB, Nrf2/HO-1, and BDNF/VEGF signaling pathways." (PMID 39650161, 2024). "Hence, our data suggest that low dopamine levels could account for lower circulating BDNF levels, and thus cognitive deficit, while hinting at the intriguing possibility that its accelerated catabolism by MAO may contribute to the overall rise in ROS emission seen in deep divers." (PMID 36214902, 2023).
Cognitive impairment (continued). "In our previous study, using a mouse model of maternal sleep deprivation, we revealed that reduced levels of BDNF, PSD-95, and SYP in the hippocampus were strongly correlated with cognitive impairment." (PMID 38074521, 2023). "We found that BDNF serumlevels are lower (13.7% less) and PAI-1 levels are higher (23% more)in Alzheimer patients with dementia than in Alzheimer patients withamnestic mild cognitive impairment patients." (PMID 37810633, 2023). "Decreased serum BDNF in MDD and BD II patients with a current depressive episode, compared to HC.BDNF and cognitive deficits are both of low efficiency in distinguishing BD II from MDD." (PMID 37626577, 2023). "Cognitive impairment was assessed using the Mini-Mental State Examination (MMSE), while serum BDNF levels were measured using ELISA following standardized protocols." (PMID 37520481, 2023). "This study demonstrated that METH-induced cognitive impairment was significantly improved by administration of BER, possibly by promoting the expression of neurotrophins in the hippocampus, including BDNF and GDNF." (PMID 36594063, 2023). "DEX promoted hippocampal neurogenesis by promoting the polarization of A1 astrocytes to A2 astrocytes and then activating BDNF/TrkB/CREB signaling pathway, thus alleviating brain injury and long‐term cognitive impairment in neonatal HIBD rats." (PMID 37830170, 2023). "Our analysis demonstrates that EE exposure can improve postsurgery SD‐induced cognitive impairments with upregulated brain‐derived neurotrophic factor (BDNF) and GluA1 expression, which indicates that EE exposure could promote postsurgery SD‐induced cognitive impairments through BDNF/GluA1 pathway." (PMID 37095708, 2023). "The pattern of BDNF changes varied between T2DM, prediabetes, and control groups depending on cognitive impairment." (PMID 36936159, 2023). "In humans, aerobic exercise (30 min of moderate-intensity exercise at 65–75% of target heart rate reserve) significantly increases the serum levels of BDNF, IGF-1, and VEGF in elderly people with mild cognitive impairment." (PMID 37600508, 2023). "We then examined the role of BDNF and TrkB in mediating ELS-induced cognitive impairment by specifically downregulating or upregulating BDNF levels (Exps." (PMID 37225683, 2023). "Another study also reported the downregulated expression of BDNF, NGF, and GDNF in patients with mild cognitive impairment and moderate AD." (PMID 36983803, 2023). "Cognitive impairment is anotable complication of type 2 diabetes (T2DM), accompanied by reduced brain-derived neurotrophic factor (BDNF) in the brain and blood." (PMID 38001940, 2023). "We noticed that T2DM patients had significant alterations in their cytokine levels, BDNF levels and SBM indices prior to the development of cognitive impairment." (PMID 37113152, 2023). "Altogether, Rg1 and Rb1 treatment attenuated cognitive deficits induced by HLS, mitigated mitochondrial dysfunction, attenuated oxidative stress, inhibited apoptosis, increased synaptic plasticity, and restored BDNF-TrkB/PI3K-Akt signaling." (PMID 37168997, 2023). "DEX promoted neurogenesis in the hippocampus by activating the BDNF/TrkB/CREB pathway through the induction of polarization of A1 astrocytes toward A2 astrocytes, subsequently mitigating neuronal damage and cognitive impairment in neonates with HIBD." (PMID 37830170, 2023). "The BDNF-ERK-CREB pathway is fundamental for neuronal survival, synapses, and synaptic plasticity and it is also involved in cognitive impairment." (PMID 37569811, 2023). "As a result, the development of cognitive impairments and a reduction in CREB and BDNF production in the hippocampus are closely related." (PMID 38323121, 2023). "In this paper, we also observed that the administration of BDNF-eMSCs reduced TBI-induced pathological outcomes such as neuronal death, neurological deficits, and cognitive impairment." (PMID 36986535, 2023).
Cognitive impairment (continued). "Moreover, the p75NTR inhibitor and the exogenous BDNF could rescue surgery-induced imbalance of BDNF and its precursor, and establish a relative new ratio homeostasis, which further ameliorates the synaptic dysfunction and cognitive impairment." (PMID 35370607, 2022). "Hutten and colleagues reported dose-dependent positive effects on mood, but also anxiety and cognitive impairment; also, the same group showed that low doses of LSD can increase brain-derived neurotrophic factor blood plasma levels in healthy volunteers." (PMID 35918311, 2022). "We then compared the serum levels of soluble factors including 5-HT, GABA, BDNF, GR, CRH, IL-6 and TNF-α in preterm rats from the normal control group and cognitive impairment group." (PMID 36061856, 2022). "In order to explore the potential mechanisms of sevoflurane-induced cognitive impairment and AHN inhibition, we evaluated the effects of sevoflurane exposure on the expression levels of BDNF/TrkB and NT-3/TrkC in the hippocampal tissues of aged mice." (PMID 35309893, 2022). "Apigenin improves cognitive impairments in the rat model of post-stroke cognitive deficits, through decreased HDAC content, up-regulation H3 and H4 acetylation in the hippocampus and increased the level of BDNF in dose-dependent manner." (PMID 36415642, 2022). "The genes of cognitive impairment regulated by non-coding RNAs include GRIN2A, BDNF, HTR2A, and NMDAR." (PMID 36406755, 2022). "Our findings indicated that resveratrol alleviated pain and improved cognitive deficits, probably by regulating neural ultrastructure remodelling and the CREB/BDNF pathway." (PMID 36478990, 2022). "Brain-derived neurotrophic factor (BDNF) plays an important role in neural survival, synaptic plasticity, and long-term potentiation (LTP); thus, its alterations are correlated with cognitive impairments." (PMID 35892669, 2022). "The genes of cognitive impairment modified by DNA methylation include GAD1, BDNF, DRD3, DRD4, and 5HTR1A." (PMID 36406755, 2022). "In doxorubicin (DOX)-impaired rats, galangin significantly mitigates cognitive impairment and neurotoxicity via the NOX-1/Nrf-2/HMGB1/TLR4 and TNF-α/MAPKs/RIPK/MLKL/BDNF pathways." (PMID 36015161, 2022). "Accordantly, preoperative resistance exercise improved surgery-induced adverse effects including cognitive impairment, synaptic deficit and neuroinflammation, possibly by facilitate mitochondrial health through the PGC1-a/BDNF pathway." (PMID 35705955, 2022). "Taken together, CH mediates cognitive impairment of pups through the inactivation of CaMKIV in the hippocampal neurons, which decreases the expression of EGR3 and further reduces the production of BDNF, thereby impairing the growth of dendritic spines." (PMID 36473844, 2022). "From the identified BDNF/GSK-3β/β-catenin axis, dysfunction of Wnt signaling is enough to encourage a neuropathological process incorporated in AD as cognitive impairment and aggregation of Aβ." (PMID 35668264, 2022). "It was reported that MCI and AD patients displayed massive reductions in the levels of proBDNF (21% / 30%) and BDNF (34% / 62%) in the parietal cortex that preceded acetylcholine dysfunction and correlated with cognitive impairments." (PMID 36117625, 2022). "Indeed, the overexpression of BDNF blocks hyperglycemia-induced microglial activation and prevents the elevations in TNF-α, IL-1β, and nuclear factor-κB (NF-κB), thereby reducing the central neuroinflammatory components associated with diabetic memory and cognitive impairments." (PMID 35955546, 2022). "In the present study, chronic resveratrol treatment significantly alleviated pain and ameliorated TN-induced cognitive deficits by restoring the ultrastructure of hippocampal neurons and synapses and upregulating the CREB/BDNF pathway in the hippocampus." (PMID 36478990, 2022).
Cognitive impairment (continued). "PTX (10 mg/kg) induced significant cognitive impairment, accompanied by changes in synaptic plasticity, including decreased density of PSD95 (0.65-fold), BDNF (0.44-fold) and dendritic spines (0.57-fold)." (PMID 35944285, 2022). "Another report indicated that resveratrol treatment ameliorates chronic unpredictable mild stress-induced depressive-like behaviour and cognitive deficits by upregulating CREB and brain BDNF." (PMID 34646421, 2021). "In the present study, the repeated injection of LPS induced activation of NF-κB and expression of IL-1β and TNF-α and suppressed expression of BDNF and phosphorylation of CREB in mouse brain, resulting in cognitive impairment, as previously reported." (PMID 34579150, 2021). "Simultaneously, chronic HPTQ treatment debilitated diabetes-induced cognitive deficits and regulated hippocampal insulin metabolism activated CREB/BDNF/TrkB signaling pathway and suppressed the mitochondria-related Bax/Bcl-2 and caspase-3 apoptosis pathway." (PMID 34211563, 2021). "Studies show that BDNF is reduced in people with dementia, mild cognitive impairment (MCI), and AD and that higher BDNF in the brain and systemic circulation is associated with a slower rate of cognitive decline in individuals diagnosed with MCI or AD." (PMID 33661922, 2021). "The possible underlying molecular mechanism by which CoQ10 alleviates phenytoin-induced cognitive impairment is related to VEGF and enhances the BDNF-TrkB-CREB signaling pathway in the hippocampus and cortex of phenytoin-treated rats." (PMID 34574891, 2021). "DC and DD alleviated LPS-induced cognitive impairment-like behaviors in the Barnes maze task more strongly than DW2009 or C29 alone, while BDNF expression and CREB phosphorylation in the hippocampus were more strongly increased." (PMID 34579150, 2021). "A meta-analysis found that the reduced brain-derived neurotrophic factor (BDNF) levels and elevated C-reactive protein (CRP) in SCZ had a significant relationship with cognitive impairment, particularly in subjects with chronic SCZ." (PMID 34354618, 2021). "Even BDNF DNA methylation is affected in a PTSD rat model, possibly leading to the persistent cognitive deficits typical of PTSD." (PMID 33477654, 2021). "Due to their differentiation ability and endocrine function, stem cells are a plausible therapy to alleviate ischemia-induced cognitive impairments by targeting CREB and BDNF concentrations." (PMID 32731545, 2020). "Our study provides evidence to show that harmine can mitigate cognitive impairment in STZ-induced diabetic rats and exert neuroprotective effects through inhibiting NLRP3 inflammasome activation and enhancing the BDNF/TrkB signaling pathway." (PMID 32425784, 2020). "Fto knockout mice show low expression of BDNF and disturbed ratio of proBDNF and mature BDNF in the hippocampus and have impaired working memory, while Fto depletion slows down the cognitive impairments in mouse models of Alzheimer’s disease." (PMID 32647628, 2020). "Meanwhile, we would like to evaluate the relationship between BDNF or GDNF levels and cognitive impairment in DS." (PMID 31420036, 2019). "Findings from previous studies reporting the levels of serum brain-derived neurotrophic factor (BDNF) in patients with Alzheimer’s disease (AD) and individuals with mild cognitive impairment (MCI) have been conflicting." (PMID 30634650, 2019). "These mice had lower levels of brain-derived neurotrophic factor (BDNF), a higher number of cognitive deficits, and poor performance in the MWM." (PMID 31572381, 2019). "To determine whether GQ1b improves cognitive impairments in transgenic mouse models of AD, we used 3xTg-AD mice at advanced stages of the disease (18–22 months), that had already developed Aβ, tau pathology and showed decreased BDNF expression in the hippocampus." (PMID 31186474, 2019).